IGHJ1 (immunoglobulin heavy joining 1)
Description:
J region of the variable domain of immunoglobulin heavy chains that participates in the antigen recognition. Immunoglobulins, also known as antibodies, are membrane-bound or secreted glycoproteins produced by B lymphocytes. In the recognition phase of humoral immunity, the membrane-bound immunoglobulins serve as receptors which, upon binding of a specific antigen, trigger the clonal expansion and differentiation of B lymphocytes into immunoglobulins-secreting plasma cells. Secreted immunoglobulins mediate the effector phase of humoral immunity, which results in the elimination of bound antigens. The antigen binding site is formed by the variable domain of one heavy chain, together with that of its associated light chain. Thus, each immunoglobulin has two antigen binding sites with remarkable affinity for a particular antigen. The variable domains are assembled by a process called V-(D)-J rearrangement and can then be subjected to somatic hypermutations which, after exposure to antigen and selection, allow affinity maturation for a particular antigen.
Synonyms: JH1
Gene: Immunoglobulin joining (J) gene on chromosome 14 (105,865,407 to 105,865,458, reverse strand). Ensembl gene ENSG00000211905.
Subcellular location: Secreted; Cell membrane
Gene Ontology:
Cellular component: extracellular region; plasma membrane